CCL4 (C-C motif chemokine ligand 4)
Diseases named in the same sentence as CCL4 in open-access papers (continued):
Sharing a sentence is not in itself a finding about the gene and the disease.
tumor (continued). "Intratumoral CD8+ T cells were enriched in CXCL13 and CCL4 expression, mediators of immune cell recruitment, although whether this has a positive or negative influence on tumor growth is unclear." (PMID 36253784, 2022). "Also in contrast to CCL3/MIP-1α, significant differences were observed only in tumors from old stressed mice, which had higher tumor CCL4/MIP-1β levels than tumors in young non-stressed mice (p<0.05)." (PMID 34604038, 2021). "Moreover, CCL4 might contribute to TME modulation, indicating the mechanism CCL4 involved in tumor proliferation and metastasis, which could provide novel therapeutic perceptions for ccRCC patients." (PMID 34900664, 2021). "Also, a role for “patrolling” monocytes (PMo) in regulating NK cell anti-tumor activity has been delineated in a murine model of lung cancer where PMo induced NK cell recruitment through secretion of high levels of CCL3, CCL4, CCL5 and their activation in the tumor site." (PMID 34975880, 2021). "Moreover, we observed that the production of CCL4, CCL5, CXCL9 and CXCL10 chemokines was induced by the co-culture of murlentamab-opsonized SKOV3-R2+ tumor cells with both M0 and TAM-like MDMs, while the normal fucosylated form 3C23K-CHO did not demonstrate any effects." (PMID 33924378, 2021). "Muscle-derived CCL4 has not been attributed with direct anti-tumour effects yet." (PMID 34359731, 2021). "Furthermore, tumor hyperthermia potentiated immune system responses through release of exosomes containing chemokines (CCL2, CCL3, CCL4, CCL5, and CCL20), HSPs, and tumor antigens to the antigen-presenting cells and facilitated tumor cell attack and tumor cell surface modulation." (PMID 34337063, 2021). "Therefore, we measured the expression of CD103 and CCL4 in the tumor microenvironment with or without combination therapy by immunofluorescence." (PMID 32194569, 2020). "Interestingly, studies that compared tumours infiltrated by leukocytes (‘hot’) to those that excluded immune cell infiltration (‘cold’) identified more abundant CCL3, CCL4, and CCL5 in hot tumours, including via single-cell transcriptomics that ascribed their expression to CD8+ T cells." (PMID 33046212, 2020). "However, in a tumor both CCL3 and CCL4 may be cleaved by cathepsin D and chemokine decoy receptor ACKR2/D6, which suppresses the anti-cancer effect of these two CC chemokines." (PMID 33076281, 2020). "In the melanoma mouse model, β‐catenin activation reduced the expression of tumor CCL4 gene, and dendritic cells could not be recruited by the tumor microenvironment, thus, reducing the infiltration of T cells in the tumor." (PMID 32875727, 2020). "Finally, we asked whether blocking the CCL4 signaling could abolish the recruitment of CD103+ DC and CD8+ T cells in the tumor, and subsequent anti-cancer effects." (PMID 32194569, 2020). "In light of the patient survival curves stratified by CD8 and CCL5 tumor expression, these T cell–microglia interactions may be particularly relevant to LGGs, where MDK/CCL4-independent mechanisms involving CD8+ T cells and microglia result in CCL5 support of tumor growth." (PMID 32358581, 2020). "First, we did not explore the mechanism where expression of CCL4 by tumor cells is increased." (PMID 32194569, 2020). "However, the comparative lack of production of pro-inflammatory chemokines (e.g. CCL3, CCL4) and absence of lymphocytes in primary tissue are consistent with the failure of DIPG-associated macrophages to trigger an effective anti-tumor immune response." (PMID 29954445, 2018). "In the absence of this mechanism, (e.g. in tumours with an activated Wnt/β-catenin pathway leading to transcriptional repression of CCL-4), impaired trafficking and function of Batf3+ dependent CD8α+ DCs and a non-inflamed tumour immunophenotype are likely results." (PMID 29157300, 2017).
tumor (continued). "Thus, the higher induction of CXCL10, CCL4 and GMCSF mRNA exhibited by the good responder group was not unexpected and suggests that these patients may have greater anti-tumour immunity." (PMID 26115406, 2015). "Recently, it was demonstrated that mouse tumor-infiltrating granulocytic and monocytic (MO-MDSC) myeloid-derived suppressor cells expressed increased levels of chemokines comprising the CCR5 ligands CCL3, CCL4, and CCL5, and they were responsible to recruit high numbers of Tregs." (PMID 24591756, 2014). "However, Condition medium (CM) with neutralizing antibody CCL4 had no significantly affect on tumor cell invasion." (PMID 23577100, 2013). "Furthermore, α-TEA treatment modulated the tumor microenvironment in a proinflammatory fashion, as we found significantly higher IL-6 and CCL5 levels and a trend toward higher levels of other proinflammatory mediators (IL-1β, CCL2, CCL3, CCL4)." (PMID 21232138, 2011). "So far, we have identified CXCL1, IL10 and CCL4 in exercise-conditioned serum of advanced PC patients; it will be important to know if these myokines are generally induced by exercise, independent of the tumour type and its characteristics (e.g., aggressiveness or hormone dependency)." (PMID 34359731, 2021). "Thus, to examine whether there are common tumor-promoting factors between parent and resistant cells that enhance neutrophil survival, we tested the expression of pro-inflammatory factors such as IL-1β, CCL2, CCL3, CCL4, IL23, and iNOS in neutrophils." (PMID 33049964, 2020). "In accordance with MIF and CXCL8, the clinical significance of CCL4 was not consistent, even opposite, in different cancers, suggesting that the biological functions of these cytokines in tumorigenesis and therapy response are complicated and labile and may be tumor type-specific." (PMID 40092701, 2025). "The constructs harboring CCL4 and CCL19 as APC-binding molecules were the most efficient, with CCL19_Neo5 leading to statistically significant tumor control compared to the non-targeted construct NT_Neo5." (PMID 37720215, 2023). "Compared to normal tissue from non-cancer patients, the CCL3, CCL4 and CXCL2 expressions were upregulated in both tumor and tumor-adjacent tissue, while CCL19 was upregulated solely in tumor-adjacent tissue." (PMID 34885960, 2021). "The expression of CCL4 and CXCL2 from MIP chemokines was significantly, and CCL3 insignificantly, upregulated in tumors compared to tumor-adjacent non-transformed tissue by 1.4-fold, 2.0-fold, and 1.3-fold, respectively." (PMID 34885960, 2021). "The non-paired analysis confirmed significantly higher CCL19 and significantly lower CCL4 and CXCL2 expression in tumor-adjacent tissue than in tumors, and a lack of difference in the case of CCL3." (PMID 34885960, 2021). "However, the differences in CCL5 and CCL4 expression between IL-32–treated tumors from WT and Batf3–/– mice were not statistically significant, suggesting that DC are not exclusively responsible for the increased tumor chemokine levels in response to IL-32 treatment." (PMID 32841222, 2020). "Furthermore, tumor-infiltrating monocytic myeloid-derived suppressor cells (MO-MDSC) and granulocytic myeloid-derived suppressor cells (PMN-MDSC) from B16-bearing mice could produce higher levels of CCL3, CCL4, CCL5 than that in control mice at melanoma sites, especially MO-MDSCs." (PMID 30800130, 2019). "As assessed by qRT-PCR on tumor fragments, IR treatment increased expression of CXCL10 and CCL5, but not CCL4." (PMID 27343548, 2016). "The presence of tumor cells was sufficient to upregulate several other pro-inflammatory cytokines and chemokines, including tumor necrosis factor alpha, IL-6, chemokine C-C motif ligand 3 (CCL3), and CCL4, regardless of anti-PD-L1 treatment." (PMID 41050935, 2025). "In addition, we constructed a DEN/CCL4‐ induced HCC mouse model and found that FDFT1 expression was obviously higher in tumor tissues than in nontumor tissues." (PMID 39899681, 2025).
tumor (continued). "Interestingly, the TCM from the poorly immunogenic tumor CT26 and recombinant IL6 alone did not modulate CCL3 or CCL4 production." (PMID 35064009, 2022). "When compared to exosomes from tumor cells without heat stress (TEX), heat-stressed tumor cell-derived exosomes (HS-TEX) had more chemokines (CCL2, CCL3, CCL4, CCL5, and CCL20), HSPs (HSP60, HSC70, HSP70, and HSP90), and adhesion molecules (e.g., CD54 and CD86)." (PMID 35158999, 2022). "Finally, we performed non-parametric correlation (Spearman) analysis for CCL4 in the subcutaneous adipose tissue and for CCL3 in the tumor, having found a statistically significant positive correlation (p = 0.0448) only for the cachectic patients." (PMID 26732354, 2015). "Further, 4-culture tumor spheroids decreased the concentrations of T-cell chemoattracting cytokines, i.e., CCL4, CCL5, and CXCL9, when compared with the non-cancerous spheroids, revealing a critical immunosuppressive feature of the different types of cells forming the tumor spheroids." (PMID 37519820, 2023).
infection (319 papers, 2007 to 2026). The state of being infected such as from the introduction of a foreign agent such as serum, vaccine, antigenic substance or organism. "IL‐37 mitigates the infiltration of macrophages and suppresses the production of macrophage‐associated chemokines (such as CCL3 and CCL4) induced by SARS‐CoV‐2 Omicron infection through NF‐κB signaling pathway." (PMID 40452816, 2025). "Additional cytokine/chemokine transcripts induced by invasive infection were e.g., Ccl3, Ccl4, Ccl7, Cxcl10, and Csf2 (encoding GM-CSF)." (PMID 38291037, 2024). "Our study showed that CPP-Se increased CCL4 expression and presumably increased the resistance to pathogenic infection." (PMID 37235428, 2023). "Other markers in this study were associated with M. leprae colonization (IL-1Ra), whereas CCL4 was associated with infection and disease." (PMID 32849645, 2020). "This is consistent with the fact that the up-regulation of different cytokine encoding genes such as IL-1β, TNFα and CCL4 by MEC is restricted at the very early stages of infection, before a decrease at 30 hpi." (PMID 24521038, 2014). "Notably, chemokines like CCL4 have been implicated in viral restriction via metabolic modulation, suggesting immune–metabolic crosstalk during infection." (PMID 41042757, 2025). "However, TNF-α expression was detected in Delta infection, albeit later and milder than the previous variants, indicating that its regulation is independent from that of CCL4 and IL-6." (PMID 36073824, 2022). "Plasma levels of the monocyte chemoattractant CCL4 on the other hand were reduced, which potentially could increase susceptibility to infection." (PMID 30131724, 2018). "The protein expression of two proteins (CCL4 and CCL25) significantly decreased in caspase-1-deficient cells compared to Cas9 cells following HK1651 infection." (PMID 40137780, 2025). "The factors secreted by the parasite, during the chronic form of infection, stimulate the production of interleukin 12 from dendritic cells and macrophages, as well as the interaction between chemokines, such as CCL4, CCL5 and CCL3." (PMID 40855457, 2025). "CCL4 mRNA was highly induced during the first hours of infection (1.5 to 3 h.p.i), and peaked again at 24 h.p.i." (PMID 40934228, 2025). "Cluster 0 myeloid cells emerged as a prominent population post‐PA infection, characterized by the expression of Il12a, Il1a, Ccl4, and Csf3 genes, indicative of a pro‐inflammatory M1‐like phenotype." (PMID 40087815, 2025). "The increased interferon and inflammatory module expression in Th17 cells and BECs also correlated with increased measured levels of IFN-α, CCL4, and IL-1β following infection." (PMID 41332562, 2025). "The high expression level of ccl4 gene in the chronic form of infection plays an important role in the transfer and control of immune cells to the sites of infection." (PMID 40855457, 2025). "Conversely, Pad2−/− mice showed a downregulation of M1‐related genes (Il1a, Il1b, Tnf, Cxcl2, Ccl4, Il12a, Cxcl1, Il6) compared to WT mice after PA infection." (PMID 40087815, 2025). "The results showed that in the rVSV-WT group, the levels of TNF-α, IFN-γ, and CCL4 were significantly higher at 24 h post-infection compared to the rVSV-M2 and rVSV-M4 groups." (PMID 40872776, 2025). "Our findings revealed a significant upregulation in the Ccl3 and Ccl4 mRNA expression in isolated and differentiated M1 macrophages 24 h after BA.5 infection." (PMID 40452816, 2025). "Greater CCL5 activity was predicted in C57BL/6 mice at 20 days after infection, whereas predicted activity of the chemokines CCL6, CCL9, CCL3, and CCL4 was highest in C3HeB/FeJ mice by 20 days after infection." (PMID 40986319, 2025). "IL-8 and CCL4 are chemokines produced by macrophages that have chemoattractant activity for neutrophils and T cells at sites of infection." (PMID 40509121, 2025).
infection (continued). "Analysis of macrophage‐related cytokines and chemokines found that Tnf, Il1b, Il1a, Ilrn, Il17ra, Cxcl1, Cxcl2, Ccrl2, Ccl3, Ccl4, and Ccl9 expression significantly increased over the course of infection." (PMID 41117166, 2025). "In contrast, the classical CD11b+Ly6C+Ly6G− monocytes are attracted to the site of infection by Type I IFN-stimulated production of CCL4 and also moderate tissue damage, possibly by becoming infected and soaking up excess virions." (PMID 38543790, 2024). "Chemokine-related genes CXCL9 and CXCL10 were significantly up-regulated in the early phase of infection, while CCL4 was significantly up-regulated in the late phase of infection." (PMID 39026675, 2024). "The monocyte chemoattractants CCL2 and CCL4 were significantly increased in mice infected with both Em and Bb, relative to vehicle or single Bb infection, and CCL7 was significantly increased in co-infected mice relative to Em alone." (PMID 39229265, 2024). "CC chemokines have been shown to play an important role in inflammation, as both CCL3 and CCL4 orchestrate the immune responses to infection or inflammation." (PMID 39058144, 2024). "T cells secrete numerous chemokines including CCL2, CCL3, and CCL4, which direct cellular recruitment to the site of infection." (PMID 38977711, 2024). "We also analyzed the expression of chemokines CCL2, CCL3, and CCL4, which are synthesized in response to infection and play an important role in the recruitment of monocytes/macrophages to inflammation sites." (PMID 38674602, 2024). "Over the infection time, the levels of CCL4 became equivalent in the two groups and continued to increase until day 10 after infection." (PMID 37563696, 2023). "MVA∆E5R infection of BMDCs potently upregulated Ifnb1, Ifna, Ccl4, and Ccl5 gene expression, whereas MVA infection had modest induction." (PMID 37217469, 2023). "Cytokines and chemokines in serum revealed an increase in the pro-inflammatory chemokines CXCL10 and CCL4 at week 4 post infection." (PMID 37837930, 2023). "In AGM, the expression of Ccl2, Ccl3, Ccl4, Ccl7, and Ccl8 together with Cxcl10 and Cxcl11 also increases during infection, although more rapidly and with a more marked expression in nonpolarized rAM than in hamsters." (PMID 37350967, 2023). "Typical inflammatory chemokines, including Ccl4, Ccl3, Cxcl2, Cxcl3, and Cxcr2, induces immune cells to enter the site of infection during the immune response." (PMID 37580334, 2023). "In some patients, we were even able to detect an increase in certain cytokines, such as CCL3 or CCL4, 33 days after the suspected date of infection (Figure A3)." (PMID 35458486, 2022). "Our results demonstrated that vaccine strain MDV/CVI988 infection resulted in high levels of CCL4 expression in the key lymphoid organs of the chicken, particularly in the bursa infected at 7 dpi and the spleen within 21 days after infection." (PMID 36680047, 2022). "Remarkably, NK cells produce the CCL4/MIP-1β that drives inflammatory cells to the site of infection." (PMID 35456119, 2022). "The CCL4 gene encodes the protein MIP-1b that can bind HIV-1 co-receptor CCR5 and inhibit infection." (PMID 36175869, 2022). "As an inflammatory protein, CCL4 coordinates the immune response to infection or inflammation and promotes the expression of pro-inflammatory cytokines including TNF—α, IL-6 and IL-1 β in activated macrophages and fibroblasts during inflammation." (PMID 35287569, 2022). "This confirmed a significant increase in Il1b at 24 h following infection, with minimal induction of Il23a evident, as well as higher levels of monocyte and T cell chemoattractants Ccl4 and Ccl5." (PMID 35845169, 2022). "We found the levels of CXCL1, IL-6, IL-1β, CCL3 and CCL4 were higher in the kidney homogenates of female mice infected with the eng1 strain at days 1 and 4 post-infection in comparison to that infected with the ENG1 strain." (PMID 34995333, 2022).